TGFB1 (transforming growth factor beta 1)
Diseases named in the same sentence as TGFB1 in open-access papers (continued):
Sharing a sentence is not in itself a finding about the gene and the disease.
tumor (continued). "In this study, we propose to examine the effect of Fangjihuangqi Decoction on triple‐negative breast cancer and EMT in TGFβ1‐treated MDA‐MB‐231 cells and xenograft tumor zebrafish model, which as a chemotherapy drug is clinically more convenient and helpful for TNBC treatment." (PMID 32037729, 2020). "Interestingly, when we measured the total uptake of the nanoparticles within the tumor, the combined DC101 and anti‐TGFβ1 antibody treatment did not result in an increase in the unit accumulation of nanoparticles as compared to DC101 treatment alone." (PMID 30886813, 2019). "However, it is also notable that a series of genes that are expressed in activated CD8+ T cells (Gzmb, Prf1, Il2, Ifng, Tnf, Fasl) or in activated CD4+ T cells (Tgfb1, Cd40lg, Il2, Ifng, Tnf, Fasl) were not upregulated in the relevant CD8+ and CD4+ clusters in tumours versus normal." (PMID 40473819, 2025). "Therefore, and since we observed no significant increase of Tgfb1 mRNA expression or of FoxP3+CD4+ Tregs in βΑ tumors, we wondered whether Activin-A stimulates tumor growth by promoting IL4 signaling." (PMID 35580932, 2022).
cancer (9,385 papers, 1994 to 2026). A tumor composed of atypical neoplastic, often pleomorphic cells that invade other tissues. "EMT is strongly driven by the TGFβ/Smads signaling pathway, which is activated by proteins secreted by cancer cells and DCIS-associated MECs, such as TGFβ1 and αvβ6 integrin." (PMID 40563575, 2025). "The levels of EV-associated TGFβ1 are also significantly correlated with the therapeutic response to HER2-targeted therapies in HER2-overexpressing cancer." (PMID 40918454, 2025). "Pathological overexpression of TGFβ1 drives epithelial-mesenchymal transition, extracellular matrix remodeling, and cancer-associated fibroblast activation." (PMID 40145096, 2025). "Upon exposure to cancer cell-conditioned medium (CM), tMSLCs differentiate into cancer-associated fibroblasts through a TGFβ1-mediated mechanism, promoting cancer cell stemness, the EMT, and invasion." (PMID 41353504, 2025). "Using in vitro bidimensional and tridimensional cultures of cSCC cell lines, we studied the development of resistance to PDT in response to TGFβ1 secreted by cancer associated fibroblasts." (PMID 40384860, 2025). "The underlying mechanism involves cancer immune evasion via transforming growth factor beta-1 (TGF-β1) secretion by LARS B cells, driven by leucine-stimulated mitochondrial NAD+ regeneration and oxidative metabolism." (PMID 39595578, 2024). "Several studies have revealed that TGFβ1 causes cell cycle arrest, which lowers cancer cell proliferation." (PMID 38688896, 2024). "Other studies showed that YAP-TEAD activation requires TGFβ1 signaling in cancer-associated fibroblasts and pancreatic stellate cell myofibroblasts." (PMID 36835366, 2023). "As shown, TGFB1 expression was positively associated with macrophages and monocytes infiltration in most cancers." (PMID 37925591, 2023). "Chronic UV exposure causes TGFβ1/Smad3 signaling activation which contributes to cancer progression by regulating many physiological processes, including cancer cell proliferation, and invasion." (PMID 37762344, 2023). "Blocking one of these pathways (TGFβ1) established that these cells directly contribute to cancer cell proliferation and expression of genes linked to epithelial to mesenchymal transition." (PMID 36940196, 2023). "TGFβ1-activated cancer-associated fibroblasts (CAFs) promote BC growth and metastasis in part through autophagy." (PMID 35937944, 2022). "In the field of cancer, it has been shown that inhibition of transforming growth factor-beta 1 (TGF-β1) signaling, which is implicated in cell death and differentiation, increases the number of pro-inflammatory neutrophils." (PMID 36530874, 2022). "IL1β/TGFβ1 is a trigger for fibroblast recruitment and transformation into cancer-associated fibroblasts (CAF) in CRC and endows chemotherapy resistance." (PMID 35740594, 2022). "It is encoded by the TGFB1 gene on chromosome 19q13.2 and is associated with susceptibility to cancer." (PMID 35222525, 2022). "Consistently with these reports, we found that TGFB1 was markedly upregulated in the invasive sublines, overexpressed in the cancer tissues, and associated with poor prognosis in HNC patients." (PMID 34307149, 2021). "The TGFβ1 protein is a multi-functional cytokine, and its role has been implicated in human cancers, including enhancement of proliferative and metastatic potential in human RCC cells." (PMID 35127538, 2021). "WNT4, HGF and TGFB1 are associated with the molecular signaling pathways in cancer, proteoglycans in cancer, and the relaxin signaling pathway." (PMID 33959508, 2021). "Correlation of TGFβ1 expression in cancer associated fibroblasts with other immune indicators in 90 patients with SCLC." (PMID 34095135, 2021).
cancer (continued). "This is due to the association of core fucosylation with TGFβ1, epidermal growth factor, and B cell receptors, as well as the uptake of drugs by cancer cells being dependent on the molecular interaction between cell surface proteins and drugs." (PMID 33466384, 2021). "Transforming growth factor beta 1 (TGF-β1) is a multifunctional cytokine that is associated with cancer progression and suppression of immune response." (PMID 34195245, 2021). "This latter study showed elevated TGFβ1 signaling in cancer-associated fibroblasts (CAFs) in cetuximab progressors." (PMID 34177968, 2021). "In their experiments, TGFβ1 was identified as the main inducer of decorin repression in cancer associated fibroblasts." (PMID 32477937, 2020). "More than half of secreted TGFβ1 are localised to EVs and it is commonly identified in EVs released by cancer associated fibroblasts." (PMID 33148271, 2020). "The upregulation of CLU and TGFB1 genes is associated with enhanced cancer cell proliferation and anti-apoptotic properties." (PMID 32533048, 2020). "In BMP7-expressing tumors, Tgfb1 was significantly and simultaneously decreased in myeloid cells (p < 0.001), cancer associated fibroblasts (p < 0.05), and T cells (p < 0.001)." (PMID 32117236, 2020). "Many mesenchymal-subtype carcinomas are characterized by high autocrine TGFβ1 production, but the underlying mechanisms and the biological function(s) of endogenous TGFβ are not well understood." (PMID 33266416, 2020). "Progression from preinvasive lesions to overt cancers was also associated to increased expression of potent immunosuppressive genes, among which Nt5e and Tgfβ1 have been previously shown to induce T cell dysfunction." (PMID 31439856, 2019). "The transforming growth factor-beta 1 (TGFβ1) protein is implicated in the rapid spread of cancer cells through the brain’s white matter fibers." (PMID 31649250, 2019). "Our previous study reported that TGFβ1 secretion from PCa cells was quite low compared with that from fibroblasts, especially carcinoma-associated fibroblasts." (PMID 30621175, 2019). "Our previous observation of cancer-associated reprogramming of gene expression in blood cells, including TGFB1 transcriptional alterations, also supports that suggestion." (PMID 30071009, 2018). "The expression of lncRNA H19 and miR-675 were associated with repression of extracellular matrix protein, TGFβ1, that regulate cellular migration and cancer metastasis." (PMID 29579063, 2018). "The loss-of-function mutations in TGFβ-1 signaling components in CRC are fully expressed at the transition of the adenoma-to-carcinoma stage." (PMID 29495500, 2018). "TGFβ1, secreted by cancer-associated fibroblasts, induces an epithelial-mesenchymal transition of bladder cancer cells in a mechanism dependent on ZEB2NAT expression." (PMID 28671581, 2017). "CAFs secrete TGFβ1 and thus induce EMT in many carcinomas by TGFβ1-mediated loss of adherens junctions and by increased motility of cancer cells which results in enhanced invasion and metastasis abilities." (PMID 29112161, 2017). "In brief, mRNAs upregulated in response to TGFβ1 treatment are involved in hippo signaling, Wnt signaling, focal adhesion, neuroactive ligand-receptor interaction, and cancer-associated pathways." (PMID 27144026, 2016). "Activated by TGFβ-1 signaling, cancer-associated fibroblasts (CAFs) play roles in promoting cancer growth, adhesion, and invasion." (PMID 26831659, 2016). "Third, the hypomethylated genes in our signature are downstream to upstream regulators that have been implicated in cancer metastasis in numerous different studies (e.g., TGFB1, ERBB2)." (PMID 26427334, 2015). "Downregulation of TGFB1 has also been linked with the paclitaxel resistance, a mitotic inhibitor used in cancer chemotherapy." (PMID 25814785, 2015). "Proteome analyses revealed a high abundance of lysosomal enzymes and lysosome-associated proteins in cancer cells treated with TGFβ-1 and E64d." (PMID 25744631, 2015).
cancer (continued). "Past efforts have identified various SNPs (Single Nucleotide Polymorphisms) or mutations in key molecules of TGF-β1 pathway, which are associated with inflammatory, infections or human cancer including TGFB1, TβRI/II, SMADs, Foxo3A." (PMID 25909459, 2015). "S100A8/A9, NT-S100A8 are overexpressed in PDAC stroma when cancer cells express Smad4, suggesting that they are linked with TGFβ1 signalling." (PMID 24670043, 2014). "The roles of -509C>T, +869T>C and +915G>C SNPs in TGFB1 have been implicated in the etiology of various human cancers." (PMID 19835575, 2009). "Peroxisome proliferator-activated receptor-γ (PPARγ) and retinoic acid X-receptor (RXR) heterodimer, which regulates cell growth and differentiation, represses the TGFβ1 gene that encodes for the protein involved in cancer biology." (PMID 18615188, 2008). "TGFβ1 and MMPs are intricately linked in various biological processes, particularly in tissue remodeling and pathological conditions, such as cancer or fibrosis development." (PMID 40535569, 2025). "Furthermore, several studies have reported that high TGFB1 expression is associated with poor prognosis in many cancers." (PMID 36186454, 2022). "For instance, the expression of TGFb1 in stromal fibroblasts is correlated with higher invasibility by both, cancer cells as well as trophoblast cells, and is also associated with worse outcome for cancer patients." (PMID 36186235, 2022). "Additionally, TGFβ1 functions as a critical stimulus for promoting cancer cachexia, which is characterised by severe bodyweight loss resulting from skeletal muscle loss and WAT browning." (PMID 35406121, 2022). "As an endogenous EMT promoting stimulus, tumor growth factor b1 (TGFβ1), which derives from cancer-associated fibroblasts (CAFs), promotes EMT through several signaling pathways, including the TGFβR-SMADs axis; however, this mechanism is still not fully understood." (PMID 33917757, 2021). "Similar to previous studies, which demonstrated that high expression levels of TGFβ1 were associated with poor prognosis in several cancers as well as GC, further immunomodulatory gene analysis also indicated that TGFβ1 are significantly correlated with ASIRGPI and poor survival." (PMID 34804939, 2021). "Cytokines secreted by cancer-associated fibroblasts (CAFs) within various tumors influences these features, but the function in particular of TGFβ1 (transforming growth factor beta 1) is controversial and unknown in SCLC." (PMID 34095135, 2021). "As one of the well-known EMT inducer, the activation of TGFβ/Smad signaling by paracrine TGFβ1 from cancer-associated fibroblasts increases EMT-associated transcription factors, including SNAIL and ZEB2, and represses epithelial marker, E-Cadherin, in UBC cells." (PMID 34977026, 2021). "Together, these findings suggest that genetic polymorphisms in TGFB1 may be associated with cancer phenotypes in the early and later stages." (PMID 34113577, 2021). "Among these molecules, TGFβ1 is released directly or as cargo in exosomes released from cancer cells, and/or immunological cells trigger the transformation of normal fibroblast (NF) to cancer-associated fibroblasts (CAFs)." (PMID 34501347, 2021). "Interestingly, Ingenuity pathway analysis of these COL11A1-correlated genes placed TGFβ1 as a master regulator of the pan-cancer COL11A1-correlated genes and COL11A1-associated biological functions." (PMID 33668097, 2021). "Notably, Transforming Growth Factor β1 (TGFβ1) promotes cancer cell migration/invasion and is associated with poor outcome in TNBC patients." (PMID 32357907, 2020). "ANGPTL-4 is induced by TGFβ-1 and is implicated in cancer metastasis." (PMID 33139674, 2020). "In contrast, the authors showed that cancer cell growth was accelerated at sprouting neovascular tips (i.e., sprouting endothelium), which was associated with enhanced expression of Transforming growth factor beta 1 (TGF-β1) and periostin, and with the loss of TSP-1." (PMID 30647771, 2019).
cancer (continued). "In addition, TGFβ1 is also implicated in the regulation of the immune response, and systemic immune suppression and inhibition of host immunosurveillance favors cancer development." (PMID 29987196, 2018). "Moreover, P2Y12 deficiency reduced the capability of the cancer cells to stimulate the production of active TGFβ1 from platelets." (PMID 29456511, 2018). "19q holds the growth factor TGFB1 and several genes involved in cancer associated pathways." (PMID 30006612, 2018). "Overexpression of miR-373 induced loss of epithelial polarity, cytoskeletal reorganization, disruption of intercellular junctions and mitotic spindle aberrations, which were associated with upregulation of N-CADHERIN and TGFβ1 expression levels, suggesting cancer-related EMT." (PMID 27271572, 2016). "However, −509TT genotype of TGFB1 was associated with increased risk of stage II of cancer (p = 0.07, OR = 3.13, 95 % CI = 0.87–11.14)." (PMID 27220278, 2016). "Besides TGFβ1, the identification and functional verification of additional cancer or fibrosis-associated factors, EGF, FGF2 and PDGF-BB, further confirmed the functional relevance of the invasion signature." (PMID 26243655, 2015). "We found that the recruited BM-MSCs might be able to convert the normal fibroblasts to more cancer associated fibroblast (CAF)-like characteristics via alteration of secreted TGFβ-1." (PMID 26095189, 2015). "In addition, loss of responsiveness to TGFβ-1 has been correlated with tumorigenicity in many different cancer types." (PMID 25501935, 2014). "Moreover, higher TGFβ1 expression is well known to be linked to adverse reactions such as fibrosis, infection, cancer and increased infections, coupled with unwanted immune effects." (PMID 25236373, 2014). "In GG homozygous carriers, the lower expression levels of TGFBR2 may be associated with cellular disruptions in the TGFβ1 signaling pathway and induces the acquisition of aggressive cancer phenotypes." (PMID 23951322, 2013). "Moreover, NRP1 associates with TGFRI and TGFRII to enhance TGFβ1 signaling in cancer cells, augmenting canonical Smad2/3 signaling." (PMID 21747928, 2011). "Notably, MYC, SMAD3, and TGFB1 were implicated in more than four cancer hallmarks." (PMID 40149461, 2025). "In the present study, we genotyped SNPs of TNF, IFNG, IL6, IL10, and TGFB1 which are multifunctional cytokine that have been implicated in inflammation, immunity, and cellular organization and have been proposed to play important roles in infection and cancer biology." (PMID 23936772, 2013). "Derangement of the TGFβ1 signal transduction pathway, mediated by mutations or polymorphisms of its receptors and/or of the transduction molecules, SMADs, is considered to play a primary role in the development and progression of several types of cancer in humans." (PMID 22848630, 2012). "Collectively, we define a new TGFβ1/SMAD/lnc-APUE/E-cadherin axis: TGFβ1 activates lnc-APUE to promote cancer metastasis through Alu element-driven STAU1-mediated CDH1 mRNA decay and subsequent E-cadherin downregulation." (PMID 41632098, 2026). "It was also confirmed in two datasets of GEO database (GSE84787, GSE65801) that TGFβ1 showed higher expression in cancer tissues." (PMID 39991579, 2025). "Here, live PANC-1, SW620, and MCF7 cancer cells were added to TGFβ-1 (4.0 × 10−3 μg/mL), IL-6 (4.1 × 10−5 μg/mL), HGF (5.97 × 10−4 μg/mL), or untreated together with sialidase substrate 4-MUNANA (emission 450 nm, excitation 365 nm) for 1 min." (PMID 40227834, 2025). "Numerous cellular processes involved in cancer biology and therapy resistance are regulated by the TGFβ1/SMAD pathway." (PMID 40384860, 2025).